ENSG00000252800
Synonyms: LOC124900352
Gene: Small Cajal body-specific RNA gene on chromosome 14 (63,479,272 to 63,479,413, forward strand). Ensembl gene ENSG00000252800.
Gene Ontology:
Biological process: RNA processing
Cellular component: Cajal body; nucleolus